TNF (tumor necrosis factor)
Diseases named in the same sentence as TNF in open-access papers (continued):
Sharing a sentence is not in itself a finding about the gene and the disease.
tumor (continued). "Furthermore, TNF-α signaling, which was also enriched in our MI gene analysis for the comparison between predicted-sensitive cells and GEM-treated cells, has been implicated in therapy resistance, tumor aggressiveness, and immune suppression." (PMID 41209344, 2025). "TNF-α may also stimulate the growth of a microenvironment that is supportive of tumors by luring immune cells that inhibit anti-tumor immune responses and fasten tumor development." (PMID 40933989, 2025). "Moreover, previous studies have identified TNF-α as a potential predictive factor for response to therapy and overall disease progression during oncological treatment, specifically through modulation of the immunological response in the tumor microenvironment." (PMID 40299527, 2025). "Additionally, elevated TNF-α and IL-27 levels reflect abnormal immune activation and dysregulated cytokine production, which may contribute to tumor growth, immune evasion, or disease progression." (PMID 41254398, 2025). "In addition, both E-MVs and C-MVs showed immunomodulation of the tumor microenvironment with a significant increase in the M1/M2 macrophages ratio (7-fold and 22-fold, respectively) and increased levels of TNF-α in serum (1.8-fold and 2.1-fold, respectively) compared to control mice." (PMID 41148831, 2025). "CRS results from the robust activation of CAR T cells upon encounter with tumor cells, leading to a surge in pro-inflammatory cytokines, including interleukin 6 (IL-6), interferon gamma (IFNγ), interleukin 1 (IL-1), and tumor necrosis factor alpha (TNF-α), that drive systemic inflammation." (PMID 41323217, 2025). "Regulate tryptophan metabolism and SCFAs to enhance CD8+ T cell function, increase the production of IFN-γ and TNFα, reduce the inhibitory effect of Treg in the circulatory system, remodel the intestinal microbiota, and cooperate with PD-1 monoclonal antibody to exert anti-tumor effects." (PMID 40066456, 2025). "Additionally, CD8Teff cells exhibited particularly strong interactions with myCAF, activating pathways such as TNF signaling and cytokine-cytokine receptor interactions, which may contribute to immunomodulatory functions in the tumor microenvironment." (PMID 40971094, 2025). "FH FOLR1-CART activation was additionally confirmed by measurement of proinflammatory cytokines IL-2, IFN-γ, and TNFα detected in 1:1 co-culture supernatant collected at 24 hours with no or minimal cytokines detected in the supernatant from NT T cells co-cultured with tumor cells." (PMID 40919994, 2025). "However, studies have shown that lower levels of TNF may promote the death of tumor-infiltrating T cells, enhance tumor cell differentiation, and facilitate the migration of myeloid cells, thereby accelerating leukemia progression." (PMID 40861464, 2025). "Consequently, elevated HMGCR levels continuously synthesize cholesterol, while the inflammatory environment created by TNF-α may accelerate tumor progression." (PMID 41450917, 2025). "Notably, TNF-α–positive TANs accumulate at tumor boundaries, exhibit antitumor activity, and display higher expression of intercellular adhesion molecule-1 and CD95 compared with neutrophils in normal tissues, indicating their potential as prognostic indicators for CRC patients." (PMID 41320679, 2025). "In addition, using preclinical models of murine bladder cancer, we demonstrated that repeated intraperitoneal injections of DAB-1 (150 μM) inhibited tumor growth by 90% and stopped the formation of pulmonary metastasis, likely by inhibiting the TNFα/NFκB and IL6/STAT3 signaling pathways." (PMID 40807456, 2025). "EphA2 CAR-T cells showed higher killing efficiency of A549 cells and increased secretion of IFN-γ, TNF-α and granzyme B. In contrast, studies in xenograft mouse models confirmed that A549 tumor growth was suppressed and the number of cells infiltrating the tumor had elevated." (PMID 40428391, 2025).
tumor (continued). "Additionally, TNF‐α can stimulate the production of various vasoactive mediators, such as prostaglandin and interleukin, which may promote tumor proliferation and diminish immune function." (PMID 40620232, 2025). "Researchers combined oncolytic adenovirus (OAd) expressing TNF-α and IL-2 with CAR-T and found that it can promote M1 polarization of tumor associated macrophages and increase DC cell maturation, thereby significantly enhancing CAR-T infiltration and anti-tumor effects." (PMID 40469307, 2025). "Moreover, targeting TNFRSF1B signaling such as through TNF-α inhibitors could offer therapeutic benefits by mitigating inflammation and tumor development." (PMID 40547917, 2025). "Furthermore, since CXCL10 can modulate the physical tumor barrier, treatment with TNFα can increase vascular permeability, facilitating the extravasation of NP-encapsulated chemotherapy into the tumor, underscoring the versatility of this approach in combination with chemokine-based therapies." (PMID 41516196, 2025). "TNF-α transmits information to the cell nucleus through specific receptors on the cell membrane, thus producing complex biological activities such as promoting cell proliferation and differentiation, immunomodulation, inflammation mediation and anti-tumor activity." (PMID 40356928, 2025). "Notably, the interaction between HMGCR and TNF-α may synergistically promote tumor cell proliferation, invasion, and metastasis, while inhibiting apoptosis, thereby collectively driving tumor progression." (PMID 41450917, 2025). "For example, TNF-α often promotes macrophages to polarize into the M1 phenotype, which has anti-tumor properties.Nonetheless, elevated levels of IL-6 might prevent M1 macrophages from polarizing and encourage their transformation into the M2 phenotype, which supports tumor growth." (PMID 40242775, 2025). "In endothelial cells, TNF-α enhances TGF-β-induced endothelial-to-mesenchymal transition (EndMT), resulting in the generation of cancer-associated fibroblasts (CAFs) that support tumor growth via sustained Smad2/3 activation and upregulation of TGF-β signaling components." (PMID 40558596, 2025). "The higher levels of TNF-α in the serum of mC-MVs and mE-MVs treated mice demonstrate an inflammatory response induced by MV treatment and suggest MVs may be able to induce a pro-inflammatory tumor microenvironment." (PMID 41148831, 2025). "Therefore, it is supposed that TNF-α may play an important role in tumor bleeding in PitNETs by upregulating VEGF and MMP-9." (PMID 38716256, 2024). "M1 macrophages are activated by IFN-γ and tumor necrosis factor-alpha (TNF-α), which are released by Th1 cells, thus causing production of reactive oxygen species and release of pro-inflammatory cytokines (IL-12 and IFN-γ), processes which, in turn, stimulate anti-tumor activity." (PMID 39050852, 2024). "Elevated release of cytokines like interleukin-1, interleukin-6, and tumor necrosis factor α, disrupted hormone levels including growth hormones and estrogen, and alterations in the tumor microenvironment in HCC patients may all impair skeletal muscle function." (PMID 38321551, 2024). "Overall, our data reaffirms the importance of the Th17 and TNF pathway in the development of irAEs, supports further investigation into Th2 clusters and type 2 cytokines, and provides evidence of differential cytokine expression in distinct types of irAEs in a prospective, pan tumor analysis." (PMID 39403935, 2024).
tumor (continued). "It found that tumor-associated macrophages had upregulated genes regulated by IRF2, IRF7, IRF9, and STAT2, and downregulated genes regulated by Fos/Jun and IRF8, revealing decreased inflammatory response, TNF-α-induced proliferation, and reactive oxygen species production pathways." (PMID 39034998, 2024). "Fusobacterium nucleatum could activate the nuclear factor-kappa B (NF-κB) pathway to stimulate the production and release of inflammatory cytokines, such as IL-1β, IL-6, IL-8, and tumor necrosis factor (TNF), thereby creating a proinflammatory microenvironment that favors tumor development." (PMID 38787209, 2024). "On the other hand, the peritumoural microenvironment that has a persistent inflammatory state, secreting various pro-inflammatory chemokines and cytokines (e.g., MCP-1, TGF-β, CXCL12, TNF-α and various interleukins), could prime MSCs enhancing their migration to tumours." (PMID 39062449, 2024). "Moreover, TNF-α, as a pleiotropic cytokine, plays a key role in tumor immunity and inflammation." (PMID 38619623, 2024). "Loss of TNFα sensitivity leads to tumor immune evasion independent of perforin-mediated killing, suggesting that resensitizing cancer cells to TNFα-mediated killing might be a potent mechanism for killing antigen-negative tumor cells." (PMID 38195677, 2024). "In addition, TNF-α stimulates the production of other cytokines and chemokines in the tumor microenvironment, which may contribute to tumor growth, angiogenesis, metastasis, and the development of chemoresistance." (PMID 39273323, 2024). "According to previous reports, TNFα can activate T-effector cells (macrophages and NK cells) by blocking T-reg cells, which play an immunosuppressive role, as well as attracting and stimulating and activating neutrophils and monocytes to the tumor site for anti-tumor immune responses." (PMID 39664565, 2024). "Furthermore, NF-κB and STAT3 interact and cooperate in regulating the interaction of malignant cells and the tumor microenvironment, especially immune cells such as TAMs that release cell-stimulating growth factors and cytokines, including IL-6, IL-10, and TNF-α." (PMID 39061137, 2024). "Similarly, it has been demonstrated at the transcriptomic level that TNF‐induced necroptosis interacts with pro‐inflammatory NF‐κB pathways, increasing the expression levels of pro‐inflammatory factors and establishing anti‐tumour immunity." (PMID 38652105, 2024). "We documented up-regulation in the expression of IFN-γ, IL12p70, IL-18, IL-20, MIF, TNF-α, TSLP, BLC, Eotaxin-1, Eotaxin-2, IP-10, MIP-1a, MIP-3a, FGF-2, MMP-1, TNFRII and TWEAK, which are implicated in the modulation of inflammation, apoptosis, tumor growth, invasion, and angiogenesis." (PMID 38954024, 2024). "Moreover, LPS-induced activation of TLR4 promotes inflammation by stimulating the production and release of pro-inflammatory cytokines (such as TNF-α, IL-1β, and IL-6), thereby indirectly contributing to neoplasia through maintaining proinflammatory microenvironment." (PMID 39328278, 2024). "Interestingly, Jia and colleagues proposed in their functional experiment studies in AML patients that TIGIT expression might be correlated with increased secretion of IFN-γ and TNF-α cytokines and granzyme B, supporting the NK anti-tumor activity in AML." (PMID 39339180, 2024). "TNF-α, along with cytokines such as IL-6 and IL-1β, contributes to a pro-inflammatory microenvironment by recruiting eosinophils, mast cells, and Th2-polarized T cells, which enhance tumor growth through angiogenesis, stromal remodeling, and suppression of cytotoxic immune responses." (PMID 39682256, 2024). "TNF-α has pleiotropic effects, and its anticancer activity in animal models may be due to direct cytotoxicity, effects on tumor vasculature, or enhancement of specific anti-tumor immunity." (PMID 39339184, 2024).
tumor (continued). "For example, blocking IL1B expression in IL1B+ macrophages could prevent the production of angiogenesis-promoting MC4 via the IL1B/ADRB2 pathway, resulting in the inhibition of tumor growth, a reduction in the TNF+/VEGFA+ ratio, and an increase in patient prognosis." (PMID 39840068, 2024). "The chronic inflammatory response induced by tumour cells further enhances the infiltration of neutrophils, further promoting tumour progression through the secretion of interleukin-2 (IL-2), IL-6, IL-10, tumour necrosis factor-alpha (TNF-α), and vascular endothelial growth factor (VEGF)." (PMID 38496751, 2024). "Furthermore, endogenous TNF-α signaling has been an important TME factor in pro-tumor development." (PMID 38704736, 2024). "In addition, EPSs can play an anti-inflammatory and anti-tumor role by enhancing the activity of T cells, B cells, NK cells and macrophages, promoting the expression of cytokines such as TNF-α and IL-10, and inducing apoptosis of tumor cells and scavenging of free radicals." (PMID 38450163, 2024). "Finally, to further elucidate the mechanisms limiting tumor growth in SorLA-KO mice, we focused on cell death mechanisms that might be activated by TNFα itself, or by the infiltrating neutrophils." (PMID 38499808, 2024). "Moreover, the analysis of immune checkpoint genes suggested a compelling link between LINC01929 expression and TNF‐related immune checkpoint expression across multiple tumour types, which implicates its role in modulating inflammatory responses within the tumour microenvironment." (PMID 39586790, 2024). "Furthermore, research is underway that examines TNF-α’s function in the tumor microenvironment and how it interacts with other immune cells, which may result in novel treatment approaches." (PMID 39682161, 2024). "In a prior study showing efficacy of STING agonists against murine syngeneic AML models, it was speculated that, in addition to the benefits of IFN produced by host cells, therapeutic benefit might also depend on conditioning of tumor vasculature by augmented levels of TNFα." (PMID 38477596, 2024). "Also in this case, TNFα could exert either tumor inhibition or tumor promotion, depending on the cellular context and cancer stage." (PMID 39015505, 2024). "To investigate whether restored PGE2 production and signaling by tumor cells will reverse their resistance to TNF-α–induced killing, we knocked in (KI) the human PTGES gene (hPTGES) into the mouse Ptges-KO D6 clone, denoting these cells as mPtges-KO/hPTGES-KI tumor cells." (PMID 39298269, 2024). "Notably, selective ablation of both alleles of CARD11 in Tregs endowed fatal immune pathology, while partial deletion of CARD11 in only a fraction of Tregs to provoke their production of the IFNγ and TNF was sufficient to generate anti-tumor effects and avoid detectable immune pathology." (PMID 39227959, 2024). "These cells secrete certain proinflammatory cytokines, including interleukin-6 (IL-6), IL-12, IL-1β and TNF-α, and produce inflammatory mediators, such as nitric oxide (NO) and reactive oxygen species (ROS), to activate antitumor immunity at the early stages of tumor onset." (PMID 38409249, 2024). "However, the earliest effect of TNF was discovered to inhibit tumor growth." (PMID 38785735, 2024). "Additionally, wogonin treatment increases tumor cell apoptosis and enhances the cytotoxicity of TNF-α and TRAIL to tumor cells, blocks the tumor cell cycle, inhibits tumor angiogenesis, and synergizes with chemotherapy drugs through ROS and Ca2+-mediated signaling pathways." (PMID 39274982, 2024). "However, BCG therapy triggers the release of cytokines (IL-1β, IL-6, IL-8, granulocyte-macrophage colony-stimulating factor -GM-CSF- and TNF-α), which induce a rapid and abundant infiltration of neutrophils into the bladder with a cytotoxic and anti-tumor phenotype." (PMID 39682686, 2024).
tumor (continued). "The frequency of VISTA-positive immune cells within human clear cell renal cell carcinoma tumors is negatively associated with the frequency of tumor-infiltrating CD8+ T cells and granzyme B/perforin-positive or TNF-α-positive T cells, suggesting that intratumoral VISTA may suppress T-cell function." (PMID 39482534, 2024). "Therefore, TNFα-mediated cell killing might be a potent mechanism for enhancing tumor cell eradication." (PMID 38195677, 2024). "In addition, treatment of mMSC with TNF-α at the levels found in the iTCS at the point of collection demonstrates that the induction was not caused by residual TNF-α and must be attributed to an active molecule produced by the inflammatory tumor cells." (PMID 39310770, 2024). "Moreover, the elevated levels of the proinflammatory cytokines, TNFα, IL-6 and IL-1β in the tumor milieu of P. gingivalis-gavaged mice might further contribute to P. gingivalis-mediated CRC progression." (PMID 39120310, 2024). "Tumor cells trigger the coagulation cascade via the tissue factor (TF) and the induction of proinflammatory cytokines, such as tumor necrosis factor alpha (TNF-a), interleukin 1 (IL-1), interleukin 6 (IL-6), interleukin 8 (IL-8), and transforming growth factor beta (TGF-b)." (PMID 39063619, 2024). "Additionally, IL-18 signaling pathway and TNF pathway clarifying further their anti-tumor role." (PMID 39232806, 2024). "On the other hand, the suppression of pathways such as cGMP-PKG signaling, vascular smooth muscle contraction, TNF signaling, and tryptophan metabolism could indicate the tumor microenvironment's adjustment, facilitating tumor development and avoiding immune detection." (PMID 38715622, 2024). "RANK ligand (RANKL), a TNF-related molecule, has been shown to activate NF-κB in preclinical studies and thereby promote proliferative changes in the mammary epithelium as well as epithelial-mesenchymal transition, which induces tumour cell migration, invasion and metastasis." (PMID 39251829, 2024). "Furthermore, the Mast-CCL2 subgroup may activate the NF-κB signaling pathway through TNF-α, potentially playing a role in the recruitment of peripheral blood monocytes to the tumor by expressing CCL2 and CCL4 genes, thereby exerting effects in BCa." (PMID 39308672, 2024). "However, we also found the activation of TNF signaling pathway in the tumor microenvironment." (PMID 38594751, 2024). "MiR-21-5p may be activated by the phosphatidylinositol-3-kinase (PI3K), signal transducer and activator of transcription 3 (STAT3), and programmed cell death factor 4/tumor necrosis factor-α (PDCD4/TNF-α) signaling pathways, which affect inflammatory processes and tumor progression in CRC." (PMID 38584226, 2024). "Altogether, STINGel demonstrates its indirect antinociceptive impact by reducing the tumor burden through enhancing the presence of M1-like macrophages and N1-like neutrophils and concurrently activating immune response pathways through the upregulation of TNF and MIF signaling pathways." (PMID 38672274, 2024). "However, prolonged exposure to high concentrations of TNF-α levels can instead promote tumor progression and may lead to hemorrhagic necrosis." (PMID 38903721, 2024). "A synthetic phosphodiesterase-resistant cGAMP derivative was injected concurrently and 24h after mice received 10 Gy in one fraction, causing an early TNFα dependent response from the tumor microenvironment followed by T-cell mediated tumor regression, with control of distant, non-irradiated tumors." (PMID 38659582, 2024). "Finally, we observe changes in JAK1 and TNF-α in tumor tissues by immunohistochemistry." (PMID 38379418, 2024). "HCH could reverse the pathological lung tissue into approximately normal, the protein expression of Ki-67, VEGF and SMC3 were all reduced, the ROS level was reduced andSOD level was increased, the levels of IL-1β, IL-8, IL-13 and TNF-α were all reduced, the weights of tumor were reduced." (PMID 39211045, 2024).